ERVW-1 (endogenous retrovirus group W member 1, envelope)
Description:
This endogenous retroviral envelope protein has retained its original fusogenic properties and participates in trophoblast fusion and the formation of a syncytium during placenta morphogenesis. May induce fusion through binding of SLC1A4 and SLC1A5. Endogenous envelope proteins may have kept, lost or modified their original function during evolution. Retroviral envelope proteins mediate receptor recognition and membrane fusion during early infection. The surface protein (SU) mediates receptor recognition, while the transmembrane protein (TM) acts as a class I viral fusion protein. The protein may have at least 3 conformational states: pre-fusion native state, pre-hairpin intermediate state, and post-fusion hairpin state. During viral and target cell membrane fusion, the coiled coil regions (heptad repeats) assume a trimer-of-hairpins structure, positioning the fusion peptide in close proximity to the C-terminal region of the ectodomain. The formation of this structure appears to drive apposition and subsequent fusion of membranes.
Synonyms: ERVWE1; HERV-W; HERV-W-ENV; HERVW; HERV-7q; envW; ENV; HERV7Q; HERVWENV
Tractability: Small molecule: a structure with a bound ligand is known. Antibody: a drug acting on it is in phase 2 or 3 trials; UniProt places it where antibodies can reach, with high confidence; UniProt predicts a signal peptide or a membrane-spanning region; its Gene Ontology location is reachable by antibodies, with medium confidence.
Gene: Protein-coding gene on chromosome 7 (92,468,380 to 92,477,986, reverse strand). Ensembl gene ENSG00000242950.
Subcellular location: Cell membrane (Surface protein); Cell membrane (Transmembrane protein); Virion (Syncytin-1)
Gene Ontology:
Biological process: myoblast fusion; negative regulation of syncytium formation by plasma membrane fusion; syncytium formation by plasma membrane fusion; anatomical structure morphogenesis
Cellular component: plasma membrane
Homologues: Orthologues: macaque ERVW-1 (83% identical), rat LOC102549747 (18% identical), mouse BC035947 (14% identical). Paralogues in human: ERVFRD-1 (19% identical), ERVV-2 (11% identical), ERVV-1 (11% identical), ERVMER34-1 (10% identical), ERV3-1 (10% identical).
Diseases named in the same sentence as ERVW-1 in open-access papers:
ERVW-1 is named in the same sentence as 188 diseases in open-access papers, as found by Europe PMC text mining. Sharing a sentence is not in itself a finding about the gene and the disease. The quoted sentences say what the papers report.
viral infection (70 papers, 2006 to 2025). "One of the crucial adaptations from viral infections is to integrate the genetic sequence of the enveloped protein ERVW-1." (PMID 35215136, 2022).
multiple sclerosis (47 papers, 2004 to 2026). A progressive autoimmune disorder affecting the central nervous system resulting in demyelination. "ERVW-1 encodes syncytin 1, a membrane protein that contributes towards immune tolerance and is found upregulated in astrocytes and glial cells of individuals with multiple sclerosis." (PMID 26793054, 2015).
schizophrenia (43 papers, 2004 to 2026). A major psychotic disorder characterized by abnormalities in the perception or expression of reality. "Intriguingly, our previous findings demonstrate that ERVW-1, a risk factor for schizophrenia, also regulates calcium potential in schizophrenia." (PMID 37376599, 2023). "Further studies indicated that ERVW-1 induced ER stress and ER vacuolization and that GANAB participated in those processes caused by ERVW-1, showing the potential mechanism of aberrant protein homeostasis in the ER in the pathogenesis of schizophrenia." (PMID 37376599, 2023). "Our previous research has verified that endogenous retrovirus group W member 1 envelope (ERVW-1), a risk factor for schizophrenia, is elevated in individuals with schizophrenia." (PMID 37376599, 2023). "Nevertheless, no literature is available regarding the underlying relationship between ER stress and ERVW-1 in schizophrenia." (PMID 37376599, 2023). "Importantly, the abnormal expression of ERVW-1 has been implicated in various diseases, such as hepatocellular carcinoma, urothelial cell carcinoma, multiple sclerosis (MS), and schizophrenia." (PMID 37376599, 2023). "Furthermore, the evidence from our lab proves that ERVW-1 may contribute to the development of schizophrenia via various mechanisms and that it is an important risk factor for schizophrenia." (PMID 37376599, 2023). "ERVW-1 transcripts significantly elevated in schizophrenia plasma (n=44) vs. controls (n=37) (p<0.05) by qRT-PCR, negatively correlated with reduced GPX4 and SLC3A2 (p<0.05), supporting ferroptosis role." (PMID 41200560, 2025). "Based on the results of the DEG screening in schizophrenia and our previous research, we identified the genes related to ERVW-1 and ER stress in schizophrenia." (PMID 37376599, 2023). "Taken together, ATF6, BCL-2, and ERVW-1 displayed a significant correlation with XBP1 in schizophrenia." (PMID 37376599, 2023). "In summary, there was aberrant expression of ATF6, XBP1, and GANAB in the serum of schizophrenic patients, and these proteins displayed significant correlations with ERVW-1 in schizophrenia." (PMID 37376599, 2023). "The aim of our research was to investigate the molecular mechanism connecting ER stress and ERVW-1 in schizophrenia." (PMID 37376599, 2023). "Subsequent research indicated that the UPR gene called XBP1 had a positive correlation with ATF6, BCL-2, and ERVW-1 in individuals with schizophrenia using Spearman correlation analysis." (PMID 37376599, 2023). "In this study, we reported an increase in ATF6 expression in schizophrenia and its correlation with ERVW-1." (PMID 37376599, 2023). "Previous studies have demonstrated increased transcription of ERVW-1 in schizophrenia." (PMID 37376599, 2023). "Moreover, our in-depth studies have shown that ERVW-1 contributes to schizophrenia in several different ways." (PMID 37376599, 2023). "ERVW-1 has been found in the CSFs and serum of individuals with recent-onset schizophrenia." (PMID 37376599, 2023). "Additionally, our previous research suggested that CRP, IL10, and BDNF, which are regulated by ERVW-1, can be used as serum biomarkers of schizophrenia." (PMID 37376599, 2023). "Interestingly, in GSE21138, ERVW-1 exhibited a significant positive correlation with XBP1 at the transcriptional level in the prefrontal cortex of individuals with schizophrenia, suggesting a connection among ERVW-1, ATF6, and XBP1." (PMID 37376599, 2023). "However, there are no studies on ER vacuolization related to ERVW-1, an important risk factor for schizophrenia." (PMID 37376599, 2023). "Our results suggest that ERVW-1 might participate in schizophrenia by upregulating ATF6." (PMID 37376599, 2023). "Our correlation analysis results revealed a positive correlation between ERVW-1 and ATF6 in patients with recent-onset schizophrenia." (PMID 37376599, 2023).
schizophrenia (continued). "In conclusion, GANAB participates in the ERVW-1-induced ATF6-mediated UPR pathway, leading to ER stress and contributing to the pathogenesis of schizophrenia." (PMID 37376599, 2023). "In conclusion, ERVW-1 induced ER stress by suppressing GANAB expression, thereby upregulating the expression of ATF6 and XBP1 and ultimately contributing to the development of schizophrenia." (PMID 37376599, 2023). "Furthermore, we visualized the multiple correlations and regression analyses among ERVW-1, GANAB, ATF6, and XBP1 in the serum of individuals with recent-onset schizophrenia (n = 39) using a heatmap." (PMID 37376599, 2023). "Evidence suggests that ERVW-1 downregulates GANAB expression in SH-SY5Y neuroblastoma cells, activating the ATF6-mediated unfolded protein response, which upregulates CHOP and XBP1s, thereby inducing ER stress and impairing protein homeostasis in recent-onset schizophrenia." (PMID 41200560, 2025). "However, to the best of our knowledge, no literature has reported the relationship among ERVW-1, UPR, and schizophrenia." (PMID 37376599, 2023).
ZIKV infection (24 papers, 2016 to 2025). "We observed a down-regulated expression of GCM1, OVOL1, ERVW-1, and ERVFRD-1 in hTSCs following ZIKV infection." (PMID 37684223, 2023).
breast carcinoma (17 papers, 2009 to 2025). "Furthermore, additional Env proteins such as those of ERV3-1, ERVW-1, and ERVFRD-1 have tumor suppressor roles, whereas ERVV-1, ERVK13-1, and ERVMER34-1 may promote oncogenesis in breast cancer." (PMID 40387511, 2025).
endometrial carcinoma (15 papers, 2009 to 2025). A malignant tumor arising from the epithelium that lines the cavity of the uterine body. "The 5-year cumulative survival rate was 32.8% in patients with endometrial carcinoma and high ERVW-1 expression and 60.7% in those with low expression of ERVW-1." (PMID 37855856, 2023).
preeclampsia (15 papers, 2012 to 2026). Preeclampsia is a hypertensive disorder of pregnancy that is characterized by new-onset hypertension with proteinuria presenting after 20 weeks of gestation, and depending on mild or severe forms may initially present with severe headache, visual disturbances, and hyperreflexia. "Functional enrichment analysis of the 447 human-upregulated DEGs, including ADAM12, ERVW-1, KISS1, LGALS13, PAPPA2, PGF, and SIGLEC6, revealed over-representation of genes implicated in preeclampsia and other pregnancy disorders." (PMID 34154587, 2021). "Notably, several HPGs associated with invasive EVTs (ADAM12, PAPPA2, PGF), and pregnancy complications such as preterm birth and preeclampsia (ADAM12, HSD17B1, KISS1, LGALS13, PAPPA2, SIGLEC6, ERVW-1), were found to be upregulated in human compared to rhesus placenta." (PMID 34154587, 2021).
neuroblastoma (9 papers, 2006 to 2025). Neuroblastoma (NB) is the most common solid, extracranial childhood tumor. "Therefore, we investigated the relationship among ERVW-1, ATF6, and XBP1 with cytological experiments using the neuroblastoma cell line SH-SY5Y." (PMID 37376599, 2023). "Therefore, we further investigated the relationship between ERVW-1 and ATF6 using the human neuroblastoma cell line SH-SY5Y." (PMID 37376599, 2023).
hydatidiform mole (3 papers, 2020 to 2023). A gestational trophoblastic disorder characterized by marked enlargement of the chorionic villi, hyperplasia of the villous trophoblastic cells and hydropic changes. "ERVW-1 transcription was down-regulated in hydatidiform moles and gestational trophoblastic neoplasia compared to control placentas." (PMID 37855856, 2023). "Complete hydatidiform moles with further malignant transformation had a higher staining intensity of syncytin-1 surface unit, but the transcription level of ERVW-1 was not different from complete hydatidiform moles without malignant transformation." (PMID 37855856, 2023).
non-small cell lung carcinoma (3 papers, 2023 to 2025). A group of at least three distinct histological types of lung cancer, including non-small cell squamous cell carcinoma, adenocarcinoma, and large cell carcinoma. "Hypomethylation of ERVW-1 has also been detected in non-small cell lung cancer and a high level of syncytin-1 has been associated with a worse prognosis." (PMID 37855856, 2023).
pregnancy disorder (3 papers, 2021 to 2025). A disorder that is related to pregnancy. "Interestingly, aberrant methylation of ERVW-1 and perturbed expression of Syncytin-1 were observed in many pregnancy diseases associated to placental morphology alterations." (PMID 35757716, 2022).
acute myeloid leukemia (2 papers, 2022 to 2023). Acute myeloid leukemia (AML) is a group of neoplasms arising from precursor cells committed to the myeloid cell-line differentiation. "Nevertheless, we noticed that syncytin‐1 (ERVW‐1) and syncytin‐2 (ERVFRD‐1) were activated in acute myeloid leukemia (LAML)." (PMID 34318590, 2022).
bladder urothelial cancer (2 papers, 2018 to 2023). "For instance, upregulation of Syncytin-1, encoded by ERVW-1, is more frequently observed in bladder urothelial cancer compared to healthy tissues." (PMID 37780849, 2023).
gestational trophoblastic diseases (1 paper, 2023). "The reduced transcription of ERVW-1 in gestational trophoblastic diseases suggests a dysregulation mechanism in a malignant context." (PMID 37855856, 2023).
cancer (75 papers, 1975 to 2026). A tumor composed of atypical neoplastic, often pleomorphic cells that invade other tissues. "Importantly, HERVs are also silenced by KAP1-mediated heterochromatinization and aberrant expression of HERVs, and in particular ERVW-1, encoding the functional relic of a viral envelope protein, Syncytin-1, are associated with a variety of cancers and autoimmune/inflammatory conditions." (PMID 34434177, 2021).
ERVW-1 also shares sentences with these, for which no sentence is quoted: infection (423 papers); tumor (73); dengue (53); HIV-1 infection (45); COVID-19 (37); influenza (24); AIDS (21); autoimmune disease (20); bipolar disorder (12); neurological diseases (12); hepatocellular carcinoma (11); melanoma (10); systemic lupus erythematosus (10); Autoimmunity (8); lymphoma (8); colon carcinoma (7); colorectal cancer (7); Flavivirus Infections (7); amyotrophic lateral sclerosis (6); Infertility (6); leukemia (6); ovarian carcinoma (6); encephalitis (5); germ cell tumor (5); glioma (5); HCMV infection (5); prostate carcinoma (5); rheumatoid arthritis (5); seminoma (5); testicular cancer (5).
A further 143 diseases each share a sentence with ERVW-1 in 4 papers or fewer.